RNA5SP532 (RNA, 5S ribosomal pseudogene 532)
Gene: Ribosomal RNA gene on chromosome 20 (29,874,059 to 29,874,177, forward strand). Ensembl gene ENSG00000283433.
Homologues: Orthologues: chimpanzee 5S_rRNA (91% identical), chimpanzee 5S_rRNA (90% identical), macaque 5S_rRNA (82% identical), guinea pig 5S_rRNA (62% identical). Paralogues in human: 5S_rRNA (92% identical), RNA5SP528 (91% identical), RNA5SP530 (91% identical), RNA5S1 (84% identical), RNA5S10 (84% identical), RNA5S11 (84% identical), RNA5S12 (84% identical), RNA5S13 (84% identical), RNA5S14 (84% identical), RNA5S15 (84% identical), RNA5S16 (84% identical), RNA5S17 (84% identical), and 26 more.